RN7SL468P (RNA, 7SL, cytoplasmic 468, pseudogene)
Gene: Miscellaneous RNA gene on chromosome 2 (119,169,822 to 119,170,115, forward strand). Ensembl gene ENSG00000264833.
Homologues: Orthologues: chimpanzee Metazoa_SRP (97% identical), macaque Metazoa_SRP (90% identical). Paralogues in human: RN7SL2 (81% identical), RN7SL1 (80% identical), RN7SL3 (78% identical), RN7SL147P (77% identical), RN7SL47P (76% identical), RN7SL444P (76% identical), RN7SL575P (76% identical), RN7SL664P (76% identical), RN7SL398P (75% identical), RN7SL493P (75% identical), RN7SL553P (75% identical), RN7SL143P (74% identical), and 700 more.